ENSG00000267360 (novel protein)
Gene: Protein-coding gene on chromosome 19 (37,093,019 to 37,210,512, reverse strand). Ensembl gene ENSG00000267360.
Genetic constraint (gnomAD): Loss-of-function variants: 6 observed, 12.28 expected, observed/expected ratio (o/e) 0.49, 90% interval 0.27 to 0.96. Missense variants: 95 observed, 110.27 expected, observed/expected ratio (o/e) 0.86, 90% interval 0.73 to 1.02. Synonymous variants: 35 observed, 38.28 expected, observed/expected ratio (o/e) 0.91, 90% interval 0.7 to 1.21.